ALB (albumin)
Diseases named in the same sentence as ALB in open-access papers (continued):
Sharing a sentence is not in itself a finding about the gene and the disease.
glaucoma (17 papers, 2011 to 2025). Increased pressure in the eyeball due to obstruction of the outflow of aqueous humor. "According to these evidences, we here explored serum ALB levels in patients with glaucoma and revealed lower ALB levels in glaucoma than those in healthy controls." (PMID 35281459, 2022). "In this study, bovine serum albumin nanoparticles (BSA-NPs) coated with chitosan(CS) were developed for the topical delivery of tetrandrine (TET) for glaucoma management." (PMID 35384774, 2022). "Serum ALB (43.5, 42.1 45.3 g/L) and TP (71.9, 68.6 74.7 g/L) levels of glaucoma patients were significantly lower than those in the control group (ALB, 44.6, 43.1 46.6 g/L, p < 0.0001; TP, 72.5, 70.0 75.6 g/L, p = 0.0087)." (PMID 35281459, 2022). "The objective of this study was to formulate and optimize bovine serum albumin nanoparticles for the topical ophthalmic administration of TET for the treatment of glaucoma." (PMID 35384774, 2022). "A study carried out in dogs with corneal ulcers, uveitis, and glaucoma showed that the levels of tear albumin were up to 14.9 times higher in the injured eye compared to the healthy contralateral." (PMID 34326982, 2021). "A recent study showed that canine eyes with various ophthalmic diseases, such as corneal ulceration, uveitis, and glaucoma, had a higher lacrimal albumin levels than healthy eyes." (PMID 34679069, 2021). "According to these studies, urinary albumin excretion was associated with a high IOP and retinal nerve fiber layer defects, which were believed to have close relationships with glaucoma." (PMID 28006020, 2016). "Proteins identified in the albumin-depleted fraction of aqueous humor in patients with glaucoma shunt device using Liquid Chromatography/Mass Spectrometry (LC-MS/MS)." (PMID 21850163, 2011). "Our current findings demonstrate associations between ALB, BIL, NAR, NTBR, NIBL, and glaucoma." (PMID 35281459, 2022). "ALB (AUC = 0.6253, p < 0.0001), IBIL (AUC = 0.6105, p < 0.0001), NAR (AUC = 0.6673, p < 0.0001), NTBR (AUC = 0.6338, p < 0.0001), and NIBR (AUC = 0.6566, p < 0.0001) showed sufficient accuracy as diagnostic tests between glaucoma patients with controls." (PMID 35281459, 2022). "Among the identified proteins significantly altered in glaucoma, eight were further studied using semi-targeted or targeted approaches, showing higher levels of ALB, APOC3, CysC, TIMP2, A2M, PGTDS, and ENPP2, and lower levels of SOD1, in POAG patients compared to control subjects." (PMID 34439995, 2021). "Notably, LAP demonstrated the greatest capacity to differentiate severe from early-stage glaucoma (AUC ═ 0.8061, P < 0.001; Max Youden Index ═ 0.5377), surpassing all previously reported markers, including ALB, LYMPH%, total and indirect bilirubin, NAR, NTBR, and NIBR." (PMID 40440644, 2025). "We aimed to investigate the effects of albumin levels in tears on the bioavailability of two commonly used ophthalmic drugs: tropicamide, an antimuscarinic that produces mydriasis and cycloplegia, and latanoprost, a PGF2α analog used for the treatment of glaucoma." (PMID 32047429, 2019). "For glaucoma, PTGDS, GSTP1, SPD1, and CST3 were expressed significantly higher in almost all tissues; CRP, ALB, and TTR were markedly increased in the liver; MBP and TF exhibited high expression in the brain." (PMID 37052519, 2023). "In this retrospective case-control study, we aimed to compare serum ALB and BIL levels between the control group and glaucoma patients." (PMID 35281459, 2022). "Here, we conducted a retrospective case-control study, revealing that serum ALB, total BIL (TBIL), and indirect BIL (IBIL) levels were markedly lower in glaucoma patients than those in healthy controls." (PMID 35281459, 2022).
glaucoma (continued). "In the current study, we analyzed the alterations of serum ALB and BIL in combination with blood neutrophil counts, revealing that serum ALB, TBIL, and IBIL were significantly lower, while NAR, NTBR, and NIBR were significantly higher in patients with glaucoma than those in healthy controls." (PMID 35281459, 2022). "Moreover, we found negative correlations between AS and albumin (rg= -0.64) and between glaucoma and platelet (rg= -0.82)." (PMID 38702819, 2024). "Among the bottom half of the PRS distribution, higher levels of albumin were associated with no glaucoma (adjusted PNEF=0.047), while higher levels of small HDL, omega-3 fatty acids, docosahexaenoic acid, lactate, and citrate were associated with no glaucoma, albeit with an adjusted PNEF < 0.2." (PMID 39896457, 2025). "Additionally, we sought to combine ALB/BIL levels with parameters for systemic inflammation such as blood neutrophil counts as neutrophil-to-ALB (NAR), neutrophil-to-total BIL (NTBR), and neutrophil-to-IBIL (NIBR) ratios and explore the relationships between these indices and glaucoma severity." (PMID 35281459, 2022).
hyperparathyroidism (17 papers, 2013 to 2025). Hyperfunction of the parathyroid glands resulting in the overproduction of parathyroid hormone. "Combining these findings with the findings from the present study, adipose tissue browning caused by excess PTH in severe hyperparathyroidism can reasonably explain the reduction in serum albumin and muscle mass." (PMID 36176632, 2022). "In severe hyperparathyroidism, in addition to bone and height loss, the decrease in serum albumin and skeletal muscle mass as reflected by lower serum creatinine was evident." (PMID 36176632, 2022). "A decrease in serum albumin associated with severe hyperparathyroidism and its improvement after parathyroidectomy has been reported in previous small studies." (PMID 36176632, 2022). "Current screening recommendations for early detection of lithium-associated hyperparathyroidism propose an exclusive measurement of serum albumin-adjusted calcium (Aac) concentration as a single first step." (PMID 25505674, 2013). "Another aspect of the diagnosis pitfalls, apart from finding normal albumin-adjusted serum calcium and ionized calcium associated with high PTH levels, is the exclusion of secondary causes of hyperparathyroidism, as mentioned." (PMID 39518465, 2024). "The moderate and severe hyperparathyroidism (iPTH 600–1499 pg/ml and iPTH 1500 pg/ml) were related to reduced serum albumin and hemoglobin levels." (PMID 37093441, 2023). "Serum albumin and hemoglobin levels decreased as hyperparathyroidism severity increased, whereas serum ALP, calcium-phosphorus product, and bone turnover markers rose significantly." (PMID 37093441, 2023). "In this study, we also discovered that moderate and severe hyperparathyroidism (iPTH 600–1499 pg/ml and iPTH 1500 pg/ml) were related to reduced levels of serum albumin and hemoglobin." (PMID 37093441, 2023). "Patients with severe hyperparathyroidism had lower serum albumin and Cr/BSA compared with patients with PTH levels in the target range or mild hyperparathyroidism." (PMID 37484844, 2023). "Previous small studies in patients with severe hyperparathyroidism have also described a decrease in serum albumin which improved considerably after parathyroidectomy." (PMID 36176632, 2022). "Oxidative albumin ratio HNA/HMA showed a significant (p=0.001) reduction after 16 weeks of calcitriol treatment and the redox state of HSA showed a positive prediction for hyperparathyroidism and for inflammation." (PMID 30450134, 2018). "Furthermore, the moderate and severe hyperparathyroidism were related with lower levels of serum albumin and hemoglobin." (PMID 37093441, 2023). "Comparisons of serum albumin, creatinine, body weight and height between baseline with the preceding 1 and 2 years confirmed an ongoing deterioration of nutritional status among patients with severe hyperparathyroidism." (PMID 36176632, 2022). "However, we found the significant impact of serum albumin levels on hyperparathyroidism bone metabolism." (PMID 31839746, 2019). "The redox state of HSA could be used as a predictor for monitoring hyperparathyroidism and inflammation during calcitriol treatment by retarding albumin oxidation in HD patients with secondary hyperparathyroidism." (PMID 30450134, 2018). "Hyperparathyroidism was found in 2/31 (6.4%) patients (37.8 and 42.1 ng/L, respectively, nv < 36.8 ng/L), with levels of vitamin D low or within the reference range (26.7 ng/mL and 35 ng/mL, respectively) and normal albumin-corrected calcium levels (9.34 mg/dL and 9.38 mg/dL, respectively)." (PMID 40133996, 2025). "Oxidative albumin ratio HNA/HMA was associated with iPTH at 16 weeks of calcitriol oral therapy (r=0.537, p=0.039) suggesting that, HNA/HMA could be used as a marker for evaluating the reduction in hyperparathyroidism during calcitriol oral therapy." (PMID 30450134, 2018).
hyperparathyroidism (continued). "Moreover, serum albumin and Cr/BSA decreased and the proportion of patients with serum albumin < 38 g/L and serum Cr/BSA < 380 μmol/L/m2 increased from the preceding 1 and 2 years in the group with severe hyperparathyroidism." (PMID 36176632, 2022). "Symptomatic hyperparathyroidism, especially with bone involvement, high values of PTH and albumin-corrected serum calcium, and a US diameter of more than 3 cm, may be considered features of high suspicion of parathyroid carcinoma, differentiating it from the atypical parathyroid tumour." (PMID 37834940, 2023). "In severe hyperparathyroidism (SHPT) (PTH>600 pg/mL) patients, these levels were elevated regardless of serum albumin levels." (PMID 31839746, 2019).
hyperthyroidism (17 papers, 2014 to 2025). Overactivity of the thyroid gland resulting in overproduction of thyroid hormone and increased metabolic rate. "Regarding albumin levels (g/dL), patients with hyperthyroidism had an average of 38.0 ± 2.83 g/dL, euthyroid patients had a slightly higher average of 40.3 ± 4.09 g/dL, and hypothyroid patients had a lower average of 37.4 ± 6.47 g/dL." (PMID 39650928, 2024). "The proportion of albumin-bound hormones rises during hyperthyroidism: the TBG-bound thyroid hormones are removed with the plasma during TPE." (PMID 36983698, 2023). "The five most important features in the hyperthyroidism model were S-Cr, MCV, total cholesterol, ALP, and albumin." (PMID 35603277, 2022). "There were significant increases in creatinine and albumin level (P < 0.001), significant decreases in bilirubin conjugated, AST, and ALT concentrations from hyperthyroidism to euthyroidism." (PMID 34342595, 2021).
insomnia (17 papers, 2020 to 2026). A sleep disorder characterized by difficulty in falling asleep and/or remaining asleep. "Although higher serum albumin was significantly associated with worse insomnia, this relationship became attenuated when controlling for nutrition indicators and handgrip strength (Model 2)." (PMID 32711419, 2020). "This study reveals that factors such as older age, being underweight, stress, insomnia, married status, elevated white blood cell count, and low albumin levels are significant risk factors for frailty in patients with gynecological cancer undergoing surgery and chemotherapy." (PMID 41584588, 2025). "SHAP analysis revealed that pain score, postoperative insomnia, albumin level, and opioid use contributed substantially to model predictions." (PMID 42023444, 2026). "Multivariate logistic regression analysis identified several risk factors for frailty: older age, underweight status, stress, insomnia, married status, high white blood cell count, and low albumin levels." (PMID 41584588, 2025). "The most important characteristics (top 10 frequencies, from high to low) included willingness to treat, dyspnea, BUN, ALB, Neu, hemoglobin, nutritional intake, insomnia, respiratory frequency, and monocyte percentage." (PMID 41189242, 2025). "Second, seven independent risk factors affecting frailty in patients undergoing surgery and chemotherapy were identified: older age, underweight status, stress, insomnia, married status, high white blood cell count, and low albumin levels." (PMID 41584588, 2025). "Further academic evidence has justified that low albumin and hemoglobin levels can directly result in insomnia and poor sleep quality." (PMID 36329922, 2022). "Rather, we found that the serum albumin level, the estimated glomerular filtration rate, and the CCI score were associated with AKI in insomnia patients." (PMID 32891121, 2020). "In sum their work unraveled several symptom-marker connections between: higher metabolic markers and increased appetite; lower metabolic markers and decreased appetite; lower metabolic markers and insomnia; higher insulin and increased appetite; higher insulin and lower albumin and insomnia." (PMID 37972981, 2023). "Insomnia arises out of dysfunctional neurocircuitry and it is difficult to describe the direct role of previously identified biochemical parameters, e.g., serum albumin and low hemoglobin in worsening sleep quality and insomnia." (PMID 35186205, 2021). "Also, certain demographic, hematologic, and biochemical parameters, such as older age and lower serum hemoglobin, calcium, phosphorus, protein, albumin, and uric acid levels, were commonly seen in our insomnia patients in the lowest tertile of serum sodium." (PMID 32891121, 2020). "This suggests that nutrition indicators or handgrip strength could be potential confounders of the relationship between serum albumin and insomnia." (PMID 32711419, 2020).
intrahepatic cholangiocarcinoma (17 papers, 2017 to 2026). A carcinoma that arises from the intrahepatic bile duct epithelium in any site of the intrahepatic biliary tree. "Tumour morphology (tumour burden score (TBS)) and liver function (albumin‐to‐alkaline phosphatase ratio (AAPR)) have been shown to correlate with outcomes in intrahepatic cholangiocarcinoma (ICC)." (PMID 38961673, 2024). "This study investigated the prognostic value of fibrinogen/albumin ratio index (FARI) in predicting recurrence-free survival (RFS) in patients with intrahepatic cholangiocarcinoma (ICC) undergoing hepatectomy." (PMID 34284775, 2021). "It remains unclear whether the albumin–bilirubin (ALBI) grade and albumin-to-alkaline phosphatase ratio (AAPR) can predict long-term outcomes of surgically treated patients with intrahepatic cholangiocarcinoma (ICC)." (PMID 32411593, 2020). "The aim of this study is to explore the prognostic value of CRP–Albumin–Lymphocyte (CALLY) index in patients undergoing radical resection of intrahepatic cholangiocarcinoma (ICC)." (PMID 40115790, 2025). "This study evaluated the prognostic role of the albumin-to-fibrinogen ratio (AFR) in patients with intrahepatic cholangiocarcinoma (ICC) after curative liver resection." (PMID 41256327, 2025). "In this study, we evaluated the prognostic significance of γ‐glutamyl transpeptidase (GGT) to albumin ratio (GAR) in patients with intrahepatic cholangiocarcinoma (ICC) after hepatectomy." (PMID 35481993, 2022). "The present study aimed to investigate the impact of preoperative C-reactive protein to albumin (CRP/Alb) ratio on the long-term outcomes of patients with intrahepatic cholangiocarcinoma (ICC)." (PMID 32856868, 2020).
myocarditis (17 papers, 2014 to 2025). Myocarditis is a condition that is characterized by inflammation of the heart muscle (myocardium). "Low albumin levels have been linked to worse outcomes in acute myocarditis, while chronic anemia contributes to ventricular remodeling and increased cardiovascular mortality risk." (PMID 41235300, 2025). "This study aimed to investigate the association between neutrophil percentage-to-albumin ratio and in-hospital mortality in pediatric patients with acute fulminant myocarditis undergoing extracorporeal membrane oxygenation and to develop a PEACE model for predicting mortality in these patients." (PMID 40670894, 2025). "Oxidative stress plays an important role in the course of the disease in acute myocarditis, and serum albumin is the most abundant antioxidant in the whole blood." (PMID 40927299, 2025). "Our results also demonstrate that patients with fulminant myocarditis have lower serum albumin levels than those with mild myocarditis." (PMID 40927299, 2025). "The two groups were similar regarding the hemoglobin levels, erythrocyte sedimentation rates, albumin levels, and the frequency of coronary aneurysm, myocarditis, pericarditis, invasive mechanical ventilatory support, and intravenous immunoglobulin treatment." (PMID 39457150, 2024). "The feasibility of visualizing infiltration of MR+ macrophages in the early diagnosis and monitoring of treatment response of myocarditis with 68Ga-labeled mannosylated human serum albumin was reported earlier." (PMID 35548425, 2022). "After adjusted by age, fever duration before initial IVIG, WBC, CRP, ALT, ALB, TBil, Na+, SII was identified as an independent risk factor for myocarditis (p = 0.012)." (PMID 34504878, 2021). "Mean serum albumin was 3.2 g/dL (±0.4), significantly lower in the myocarditis group (p = 0.003)." (PMID 40535371, 2025). "In addition, albumin can regulate the production of nitric oxide to improve endothelial function and alleviate persistent myocardial inflammation." (PMID 38655495, 2024). "Higher levels of the systemic immune-inflammation index (SII), neutrophil-to-eosinophil ratio (NER), aspartate transferase-to-albumin ratio (AAR), and lactic dehydrogenase-to-albumin ratio (LAR) at myocarditis onset were associated with severe disease conditions." (PMID 39512372, 2024). "Thus, it seems extremely unlikely that the parenterally administered PfSPZ or the phosphate buffered saline or human serum albumin with which the PfSPZ are administered contributed to the myocarditis or contain an immunologically sensitizing agent." (PMID 24479524, 2014). "Besides, the ALB/GLB ratio was significantly lower in patients with acute myocarditis, suggesting that this ratio may be a valuable biomarker for diagnosing and monitoring myocarditis." (PMID 38303719, 2024). "Combining AST and LDH with albumin can simultaneously reflect systemic inflammation, nutritional status, and myocardial injury, thereby helping to assess the severity of ICI myocarditis." (PMID 39512372, 2024). "Univariate logistic analysis showed that WBC, NT-proBNP, Troponin I, CRP, albumin, hemoglobin levels and HALP score could predict fulminant myocarditis." (PMID 41235300, 2025). "In our study, the inflammatory parameters, including ALB, PLT, ESR, and CRP, in unresponsive patients were all higher than in responders, which also suggested that the myocarditis in IVIG‐resistant patients may be more serious than in IVIG‐responsive patients." (PMID 31173382, 2019). "Subsequently, upon comparing indicators between male and female samples, we found no such statistically significant was observed in ALB, GLB, and TP indicators among patients with myocarditis of both genders." (PMID 38303719, 2024).